TIMP2 (TIMP metallopeptidase inhibitor 2)
Diseases named in the same sentence as TIMP2 in open-access papers (continued):
Sharing a sentence is not in itself a finding about the gene and the disease.
epilepsy (2 papers, 2022 to 2023). A brain disorder characterized by episodes of abnormally increased neuronal discharge resulting in transient episodes of sensory or motor neurological dysfunction, or psychic dysfunction. "The molecules whose levels are chronically elevated in serum of patients with epilepsy (MMP-2, MMP-9, S100B, TIMP-1, TIMP-2) might be considered diagnostic biomarkers of epilepsy." (PMID 36766708, 2023). "Serum levels of MMP-9, MMP-2, TIMP-1, TIMP-2 and S100B were higher in patients with epilepsy in comparison to control group (p < 0.0001; <0.0001; 0.001; <0.0001; <0.0001, respectively)." (PMID 36766708, 2023). "Serum levels of MMP-9, MMP-2, TIMP-1, TIMP-2 and S100B are elevated in patients with epilepsy in the interictal period, which suggests chronic processes of BBB disruption and restoration." (PMID 36766708, 2023). "Mean serum levels of TIMP-2 in women with epilepsy were 155.91 ± 5.52 ng/mL, median 149.97 ng/mL vs. 142.13 ± 5.46 ng/mL and 133.84 ng/mL in men (p = 0.0172)." (PMID 36766708, 2023). "Increased expression of TIMP-2 in microglia was found in dogs with epilepsy." (PMID 36766708, 2023). "We showed that serum levels of molecules associated with BBB disruption (MMP-2, MMP-9, S100B) and restoration (TIMP-1, TIMP-2) are increased in patients with epilepsy in the interictal period, which might reflect chronic processes taking place at the BBB, even in the absence of seizures." (PMID 36766708, 2023). "Serum levels of MMP-9, MMP-2, TIMP-1, TIMP-2, S100B, CCL-2, ICAM-1, P-selectin, and TSP-2 were examined in a group of 49 patients with epilepsy who were seizure-free for a minimum of seven days and measured by ELISA." (PMID 36499038, 2022). "A set of molecules associated with BBB permeability (MMP-2, MMP-9, S100B), restoration (TIMP-1, TIMP-2, TSP-2), neuroinflammation (CCL-2), and endothelial activation (ICAM-1, P-sel) that are affected in epilepsy and can be measured in blood was selected in this study." (PMID 36766708, 2023). "CSF level of TIMP-2 was not increased in patients with meningitis complicated with epilepsy." (PMID 36766708, 2023). "The lack of correlation between serum level of TIMP-2 and MMP-2/TIMP-2 ratio might result from constitutive expression of TIMP-2 and less pronounced differences between the serum TIMP-2 levels in patients with epilepsy and control group." (PMID 36766708, 2023).
experimental autoimmune encephalomyelitis (2 papers, 2012 to 2023). An autoimmune demyelinating disease of the central nervous system that is produced experimentally in animals by the injection of homogenized brain or spinal cord in Freund's adjuvant. "Overexpression of TIMP2 exhibits antiinflammatory and neuroprotective effects, inhibits development of experimental autoimmune encephalomyelitis, attenuates ischemic brain injury, and alleviates cognitive deficits in aged mice." (PMID 38015626, 2023). "In animal models of CNS diseases, TIMP2 overexpression has been found to prevent the development of experimental autoimmune encephalomyelitis and ischemic brain injury." (PMID 38015626, 2023).
frontotemporal dementia (2 papers, 2021 to 2023). Frontotemporal dementia (FTD) comprises a group of neurodegenerative disorders, characterized by progressive changes in behavior, executive dysfunction and language impairment, as a result of degeneration of the medial prefrontal and frontoinsular cortices. "Tissue inhibitor of metalloproteinases 2 (TIMP2) is associated with various neuropathological conditions and has been demonstrated to reduce TIMP2 levels in the plasma of patients with frontotemporal dementia." (PMID 34256823, 2021).
gastritis (2 papers, 2010 to 2023). Inflammation of the stomach. "One study in adults with H. pylori-associated gastritis showed upregulated MMP-2, -9, and TIMP-2 on the surface of infiltrative mucosal lymphocytes." (PMID 37958643, 2023). "Our first observation was that children with H. pylori-related gastritis showed increased levels of plasma MMP-2 and TIMP-2 in comparison to uninfected children with gastritis." (PMID 37958643, 2023). "pylori-infected patients enrolled, 470 patients (265 with gastritis, 118 with duodenal ulcer, and 87 with gastric ulcer) received SNPs analysis of MMP-3-1612 6A > 5A, MMP-7-181 A > G, MMP-9exon 6 A > G, TIMP-1372 T > C and TIMP-2-418 G > C by PCR-RFLP." (PMID 20707923, 2010).
Granuloma (2 papers, 2013 to 2016). A compact, organized collection of mature mononuclear phagocytes, which may be but is not necessarily accompanied by accessory features such as necrosis. "CPE treatments induced positive TIMP-2 immunoreactivity in the hepatic tissues surrounding granulomas indicating that CPE has anti-fibrous activity of CPE." (PMID 27821159, 2016). "In the PZQ-treated group, mild TIMP-2 immunoreactivity was observed in the hepatic tissues adjacent to granulomas." (PMID 27821159, 2016). "Thus, it can be concluded that the observed elevation in MMP-2 and the decline in TIMP-2 expression may have contributed to collagen degradation and a consequent decrease in granuloma diameters and fibrotic areas following TELM treatment." (PMID 23829789, 2013). "However, the CPE-treated group showed only mild expression of TIMP-2, indicating that CPE treatment led to collagen degradation and a consequent decrease in granuloma and fibrotic areas." (PMID 27821159, 2016).
injury (2 papers, 2011 to 2024). Damage inflicted on the body as the direct or indirect result of an external force, with or without disruption of structural continuity. "In addition to TIMP-1, astrocyte expression of TIMP-2 has also been described in vivo following astrocyte activation after brain injury." (PMID 21631912, 2011).
Insulin resistance (2 papers, 2010 to 2017). Increased resistance towards insulin, that is, diminished effectiveness of insulin in reducing blood glucose levels. "Insulin resistance may therefore partly explain our observation of raised TIMP-2 levels in those women with a history of RPL." (PMID 20565712, 2010).
intervertebral disc degeneration (2 papers, 2012 to 2021). "Compared with normal nucleus pulposus (NP) tissues, intervertebral disc degeneration (IDD) samples exhibited higher levels of circular RNA derived from TIMP2 (circ-TIMP2) expression levels." (PMID 35087566, 2021). "A dominant imbalance of MMP-3/TIMP-1 and TIMP-2 relative to ADAMTS-4 and ADAMTS-5/TIMP-3 signifies an advanced stage of intervertebral disc degeneration." (PMID 22394620, 2012). "A dominant imbalance of MMP-3/TIMP-1 and TIMP-2 relative to ADAMTS-4 and ADAMTS-5/TIMP-3 is a possible indication of an advanced, irreversible stage of intervertebral disc degeneration." (PMID 22394620, 2012). "Integrated with these reports, our findings show that a state of dominant MMP-3/TIMP-1 and TIMP-2 imbalance relative to ADAMTS-4 and ADAMTS-5/TIMP-3 imbalance may indicate an irreversible stage of intervertebral disc degeneration." (PMID 22394620, 2012).
leukaemia (2 papers, 2013 to 2023). "Additionally, TIMP-2 (tissue inhibitor of metalloproteinase 2) upregulation has been seen with increased leukemia cell line (i.e., SHI-1) invasion both in vitro and in vivo with more extensive and severe extramedullary infiltration through both MMP-2-dependent and independent activities." (PMID 36900239, 2023). "Recently, we suggested a potential role of MMP-9, MT1-MMP, TIMP-1, TIMP-2 and VEGF in the pathogenesis of canine leukaemia." (PMID 23641796, 2013).
liver cirrhosis (2 papers, 2017 to 2021). "This possibility is supported by our previous work on NIL-cirrhotic hamsters, in which both overexpression of MMP-13 and decreased expression level of TIMP-2 were accompanied by a significant regression in liver cirrhosis." (PMID 34926704, 2021).
lymphedema (2 papers, 2012 to 2022). Excess fluid collection in tissues, causing swelling. "Because lymphangiogenesis is a well described feature of filarial lymphedema, it is of interest to note the significantly deceased production of TIMP-3 as well as decreased levels of MMP/TIMP-2 ratios in filarial lymphedema." (PMID 22679524, 2012).
malignant glioma (2 papers, 2015 to 2020). A grade III or grade IV glioma arising from the central nervous system. "TIMP-2 is an endogenous MMP-2 inhibitor, and the balance between TIMP-2 and MMP-2 is a critical determinant of malignant glioma invasion." (PMID 26245666, 2015). "Our results showed that the expression of TIMP-2 was not changed, while MMP-2 activity increased depending on the radiation dose in malignant glioma cell lines." (PMID 26245666, 2015).
metastatic disease (2 papers, 2020 to 2022). "We further studied the EV-derived mRNA expression of TIMP-1, TIMP-2 and MMP-1 mRNAs in plasma EVs from two groups of ccRCC patients: patients with localized disease before and after tumor removal surgery (Group A) and patients with metastatic disease (Group B)." (PMID 32610589, 2020).
nevus (2 papers, 2020 to 2025). Nevus (or naevus, plural nevi or naevi, from nævus, Latin for "birthmark") is the medical term for sharply circumscribed[1] and chronic lesions of the skin or mucosa. "It suggested that significantly elevated FABP5, IVL, KRT6A, KRT15, KRT16, and TIMP2 proteins expressed in the CM than in the nevus tissues." (PMID 32934956, 2020). "Next, to validate differential expressions of six prognostic hub genes between CM tissues and nevus tissues, we performed IHC analysis and found significantly elevated FABP5, IVL, KRT6A, KRT15, KRT16, and TIMP2 protein expressions in the CM than in the nevus tissues." (PMID 32934956, 2020).
periodontal disease (2 papers, 2020 to 2025). "Biomarkers showing high levels in periodontal disease were salivary IL-1β, IL-4, IL-6, MMP-8, and tissue inhibitor of matrix metalloproteinases (TIMP)-2, and those in the controls were tumor necrosis factor (TNF)-α, IL-10, IL-17, and IL-32." (PMID 33383828, 2020). "The biomarkers showing elevated levels in the baseline saliva of patients with periodontal disease were IL-1β, IL-4, IL-6, MMP-8, and TIMP-2, while the control group showed high levels of TNF-a, IL-10, IL-17, and IL-32." (PMID 33383828, 2020).
rectal cancer (2 papers, 2006 to 2014). A primary or metastatic malignant neoplasm that affects the rectum. "Therefore, we classified colorectal cancer into colon and rectal cancer and examined differences in the expression of MMP-2, MMP-9, TIMP-1, TIMP-2, uPA, uPAR and PAI-1 between colon and rectal cancer." (PMID 16916471, 2006).
rectal tumor (2 papers, 2006 to 2014). "In both colon and rectal tumors, MMP-2, MMP-9 and TIMP-1 protein levels were higher than in corresponding paired normal mucosa, while TIMP-2 level in tumors was significantly lower than in normal mucosa." (PMID 16916471, 2006).
respiratory failure (2 papers, 2019 to 2023). The significant impairment of gas exchange within the lungs resulting in hypoxia, hypercarbia, or both, to the extent that organ tissue perfusion is severely compromised. "The initial studies validating [TIMP-2]•[IGFBP7] enrolled patients with cardiovascular or respiratory failure going to the ICU." (PMID 31221200, 2019). "Therefore, [TIMP-2]•[IGFBP7] testing is most often being ordered in patients at risk for AKI, including those who are hemodynamically unstable, in respiratory failure, or exhibiting Stage 1 AKI." (PMID 31221200, 2019).
stable angina (2 papers, 2021). "Decreased TIMP‐2 plasma levels were detected in CAD and decreased plasma levels of both TIMP‐1 and TIMP‐2 in ACS and stable angina." (PMID 33381894, 2021).
tuberculosis (2 papers, 2017 to 2023). A chronic, recurrent infection caused by the bacterium Mycobacterium tuberculosis. "Thus, TIMP-2, -3, and -4 can be informative markers of tuberculosis progression and targets for pharmacotherapy in M. tuberculosis infection." (PMID 37686061, 2023). "IFN-γ, IL-1β, TIMP-1, and TIMP-2 could also be prognostic markers of the course of tuberculosis." (PMID 37686061, 2023). "Thus, IFN-γ, IL-1β, TIMP-1, and TIMP-2 could be prognostic markers of the course of tuberculosis, and proteins involved in the regulation of their synthesis could be potential targets in the pharmacotherapy of the disease." (PMID 37686061, 2023). "Type I collagen had minimal effects on TIMP-1 secretion, which is increased by M. tuberculosis stimulation, or on TIMP-2 secretion, which was decreased by TB." (PMID 28646039, 2017).
Varicose veins (2 papers, 2014 to 2016). Enlarged and tortuous veins. "Increased collagen content has been shown in varicose vein pathology, for this reason active collagenase MMP-1 was measured in the present study and we have calculated the active MMP-1/TIMP-1 and MMP-1/TIMP-2 ratios." (PMID 27362269, 2016). "Our results describe a decrease in active MMP-1, total MMP-2 (while total MMP-1 is not modified in varicose veins) and an increase in TIMP-1 and TIMP-2 concentrations in varicose veins." (PMID 24505358, 2014).
vasculitis (2 papers, 2015 to 2024). "Subsequently, non-significant increases in [TIMP-2]•[IGFBP7] were found for typical HUS (P = 0.51), hypovolemia/dehydration, interstitial nephritis, nephrotoxic AKI, renal vein thrombosis, perinatal asphyxia and vasculitis." (PMID 26606754, 2015).
Airway obstruction (1 paper, 2015). Obstruction of conducting airways of the lung. "We also observed a significant negative correlation between TIMP-1 and TIMP-2 with FEV1% predicted only in the AE-COPD group, indicating that both TIMPs are associated with airway obstruction in COPD." (PMID 26126526, 2015).
alcoholic cirrhosis (1 paper, 2022). "Serum TIMP-2 showed significantly increased activity in viral cirrhosis (114.78 ± 29.41 ng/mL, p < 0.0001) as well as in alcoholic cirrhosis (171.87 ± 31.87 ng/mL, p < 0.0001) compared to normals (64.12 ± 23.61 ng/mL)." (PMID 36551935, 2022).
amyotrophic lateral sclerosis (1 paper, 2022). Amyotrophic lateral sclerosis (ALS) is a neurodegenerative disease characterized by progressive muscular paralysis reflecting degeneration of motor neurons in the primary motor cortex, corticospinal tracts, brainstem and spinal cord. "TIMP1 and TIMP 2 emerge as useful diagnostic markers in neurodegenerative diseases: TIMP 1 level elevates in the CSF in Alzheimer’s and Parkinson’s diseases as well as in amyotrophic lateral sclerosis (ALS), while TIMP-2 levels increase in Alzheimer’s and Huntington’s diseases." (PMID 36232390, 2022).
and T-cell lymphomas (1 paper, 2013). "Interestingly, in T-cell lymphomas MMP-2 qRT-PCR analysis revealed a significant positive correlation with TIMP-2." (PMID 23641796, 2013). "Significant correlations between MMP-2 and TIMP-2 (p<0.001; Spearman r=0.82) and between MMP-9 and VEGF-A (p<0.01; Spearman r=0.67) were found in T-cell lymphomas." (PMID 23641796, 2013).
ascending aortic aneurysm (1 paper, 2019). "Our study aimed to analyze MMP-2 isoforms as well as the MMP-2 activating enzymes TIMP-2 and MMP-14 in ascending aortic aneurysm and control tissue from patients undergoing CABG." (PMID 30794673, 2019).
Ascites (1 paper, 2021). Accumulation of fluid in the peritoneal cavity (between the layers of the peritoneum that lines the abdomen). "The expression of TIMP-1 was highest, followed by TIMP-2 and then TIMP-3 in CN ascites." (PMID 35047406, 2021).
Atrophy (1 paper, 2014). Any weakening or degeneration, especially through lack of use. "TIMP-2, on the other hand, reported to be down-regulated in many atrophy models, remained unchanged at the protein level throughout experimental period." (PMID 24705179, 2014).
Autoimmunity (1 paper, 2005). The occurrence of an immune reaction against the organism's own cells or tissues. "Antibodies against TIMP-1 and TIMP-2 comprised most of the anti-TIMP directed autoimmunity." (PMID 16207317, 2005).
benign meningioma (1 paper, 2024). A grade I, slowly growing meningioma. "Consistent with previous results, we confirmed a higher expression of TIMP1 and TIMP2 in the benign meningioma group." (PMID 38474106, 2024).
benign ovarian tumors (1 paper, 2012). "High TIMP-2 expressions have been found in malignant tumors compared to borderline and benign ovarian tumors while various expressions were observed for TIMP-1 in the same figure." (PMID 22200690, 2012).
benign prostatic hyperplasia (1 paper, 2017). A non-cancerous nodular enlargement of the prostate gland. "We conclude that tissue levels of MMP3 and MMP7 (finely regulated by their inhibitors TIMP1 and TIMP2) are altered in PCa compared to benign prostatic hyperplasia, which is of special relevance in elderly men." (PMID 28471417, 2017).
breast diseases (1 paper, 2021). "The co-expression profile of TIMP2 was confirmed with a larger cluster of genes across different breast diseases." (PMID 34678879, 2021).
buccal mucosa cancer (1 paper, 2013). "RT-PCR and western blot analyses were conducted to determine whether metastasis in the buccal mucosa cancer model was a result of gene regulation of metastatic mediators, specifically MMPs (MMP-2 and MMP-9) and TIMPs (TIMP-1 and TIMP-2)." (PMID 23599733, 2013).
cardiac interstitial fibrosis (1 paper, 2025). "TIMP-1 - together with TIMP-2 - is correlated to the development of cardiac interstitial fibrosis, possibly mediating CD63-Integrin β1 interaction." (PMID 41467913, 2025).
cataract (1 paper, 2008). Partial or complete opacity of the crystalline lens of one or both eyes that decreases visual acuity and eventually results in blindness. "Levels of MMP-2 and TIMP-2 in PEXG with cataract, PEXG after SLT and Cataract groups." (PMID 18939999, 2008).
cerebrovascular disease (1 paper, 2025). "The role of MMPs and TIMPs in cerebrovascular disease pathogenesis is discussed further in the “Tissue inhibitor of metalloproteinases 2 (TIMP2)” section." (PMID 40407975, 2025).
coronary artery stenosis (1 paper, 2024). "Moreover, other studies have reported higher levels of serum TIMP-2 in patients with angiographically confirmed coronary artery stenosis compared to those without stenosis." (PMID 39195176, 2024).
Cryptococcal meningitis (1 paper, 2017). Meningeal inflammation produced by cryptococcus neoformans, an encapsulated yeast that tends to infect individuals with acquired immunodeficiency syndrome and other immunocompromised states. "Our urine samples were collected at a median of 4 days after diagnosis of cryptococcal meningitis, and AKI developed at a median of 8 days on therapy, which is a different scenario to the previous studies investigating the predictive value of TIMP-2." (PMID 28752102, 2017).
dengue (1 paper, 2025). "B7, Bacillus licheniformis, and Clostridium cochlearium, along with the host genes, namely, PPME1, TIMP2, NLRC4, and RhoB, were associated with immune dysregulation in the severe dengue patients." (PMID 41417796, 2025).
dental caries (1 paper, 2020). The decay of a tooth, in which it becomes softened, discolored, and/or porous. "Single nucleotide polymorphisms (SNPs) in MMP2 (rs243865), MMP9 (rs17576), MMP13 (rs2252070), and TIMP2 (rs7501477) were investigated for their association with caries in 505 subjects, 212 caries-free subjects and 293 subjects presenting with dental caries." (PMID 32116745, 2020). "Allele frequencies for MMP2, MMP13 and TIMP2 polymorphisms were significantly different between individuals with or without dental caries." (PMID 32116745, 2020).